BRAF (B-Raf proto-oncogene, serine/threonine kinase)
Diseases named in the same sentence as BRAF in open-access papers (continued):
Sharing a sentence is not in itself a finding about the gene and the disease.
tumor (continued). "Moreover, because we concurrently assessed clinical, pathologic and tumor molecular variables such as the CpG island methylator phenotype (CIMP), LINE-1 methylation, KRAS, BRAF and PIK3CA mutations, we could evaluate the effect of TGFBR2 or BAX mutation independent of these potential confounders." (PMID 21949851, 2011). "The median OS in the group of patients with wt-KRAS and wt-BRAF tumours was 107.4 months (95% CI: 82- 132.9 months) and in the group of patients with wt-KRAS and mt-BRAF tumours 44.9 months (95% CI: 28.4- 61.5 months)." (PMID 22933967, 2011). "The molecular basis of thyroid carcinogenesis has been widely investigated, leading to the discovery of oncogenes such as BRAF, RAS, and RET as major players in tumor development and progression." (PMID 22496986, 2011). "The objective response rates in the group of patients with wt-KRAS and wt-BRAF tumours were 54.0% (CR 14.7%, PR 39.3%), while in the group of patients with wt-KRAS and mt-BRAF were 38.5% (CR 15.4%, PR 23.1%)." (PMID 22933967, 2011). "More recently, the analysis of KRAS, BRAF and PIK3CA in tumour invasion fronts, lymph nodes and distant metastases revealed a discordance between primary tumours and lymph node metastases of 31, 4 and 13%, respectively." (PMID 21139621, 2010). "Conversely, cluster 4 was mainly characterised by the presence of genes involved in signal transduction and cell structure, including a number of tumour suppressor genes (FAT-2, DCC, RASSF-4 and BRAF) that play a role in the control of cell proliferation." (PMID 20700504, 2010). "We have elucidated another mechanism by which BRAF activates MEK–ERK signaling, not only to drive tumorigenesis and tumor progression, but also potentially to allow development of de novo or acquired resistance to RAF-targeted therapies." (PMID 20141835, 2010). "Pharmacodymanic analysis of tumor tissue before and after sorafenib treatment (at 1 and 2 weeks) in two patients revealed reduction in pERK (downstream of VEGFR and BRAF) and pAKT (downstream of VEGFR)." (PMID 21048836, 2010). "From the 116 tumor blocks sampled, 50 produced DNA of sufficient quality for both MLPA and BRAF/NRAS analysis, 25 produced results for MLPA only, 21 produced results for BRAF/NRAS only and 20 did not produce any results." (PMID 20140953, 2010). "Clearly, BRAF is a remarkably versatile oncogene that can promote MEK–ERK activation and tumor progression through several mechanisms and these will require different therapeutic strategies for effective disease management." (PMID 20141835, 2010). "Again this would potentially result in BRAF-mediated activation of CRAF and possibly accelerated tumor growth." (PMID 20141835, 2010). "In contrast, knock-down of BRAF+CRAF, BRAF+PIK3CA, and MEK1/2+PIK3CA in IPC298 cells led to accumulation of cells in S or G1-phase consistent with the adverse effect on tumor growth observed in vivo." (PMID 19492075, 2009). "In in vivo tumor growth studies, tumors carrying shRNAs that target NRAS alone, or combinations of BRAF and CRAF, or BRAF and PIK3CA, showed a significant delay in tumor growth compared to the corresponding sucrose controls." (PMID 19492075, 2009). "This is consistent with the fact that targeting RAS, BRAF, CRAF, BRAF+CRAF or MEK1+2 in HCT116 resulted in decreased proliferation in vitro and delayed tumor growth in vivo." (PMID 19492075, 2009). "Importantly, patients whose tumour had BRAF or PIK3CA mutation had shorter PFS regardless of whether cetuximab was administered in the second, or third and higher lines (interaction tests P=0.5 and 0.6, respectively)." (PMID 19603024, 2009). "In contrast, mice bearing IPC298 co-expressing BRAF and CRAF shRNA showed complete inhibition of tumor growth following dox induction." (PMID 19492075, 2009). "This can be achieved by either targeting both BRAF and CRAF or BRAF and PIK3CA simultaneously in NRAS mutant tumor cells." (PMID 19492075, 2009).
tumor (continued). "We also tested these lines in vivo to see if targeting both BRAF and PIK3CA or both MEK1+2 and PIK3CA will lead to delayed tumor growth." (PMID 19492075, 2009). "Given that BRAF, CRAF, BRAF+CRAF and MEK1+2 double knock-down had an adverse effect on HCT116 cell proliferation and tumor growth, we examined the effect of targeting these genes on cell cycle progression." (PMID 19492075, 2009). "Tumour xenografts from both MDAH2774 (KRAS mutant) and SKOV3 (wild type of KRAS and BRAF) cell lines were established in a nu/nu mouse model." (PMID 19018267, 2008). "Therefore, it is not known whether the activation of KRAS or BRAF mutations alters the effects of these pathways on tumour progression." (PMID 19018267, 2008). "Four of the tumours harbouring either KRAS or BRAF mutations showed a marked reduction (<50% of DMSO control) in the cell number in the CI-1040-treated group as compared with the other 14 tumours containing wild-type KRAS and BRAF (P<0.001)." (PMID 19018267, 2008). "Consequently, it was determined that the results of LCPCR for detection of the heterozygous BRAF V600E mutation in FNA or FFPE samples containing less than 50% tumor cells may not be accurate." (PMID 16606457, 2006). "As small-molecule inhibitors are available for components of both WNT-ligand secretion (LGK974) and BRAF (dabrafenib) activation, we tested whether there was a dynamic relationship between BRAF and WNT signalling in the liver and established tumours." (PMID 41261129, 2026). "High tumor cell proliferation was associated with lower stage, absence of lymphovascular invasion, deficient MMR status, BRAF mutation, and lower tumor necrosis percentage." (PMID 41201451, 2026). "Note: If IHC reveals that the tumor has the BRAF V600E variant in cases with MSI-H or loss of expression of both MLH1 and PMS2 proteins, a sporadic tumor is likely and there is no need to proceed to genetic testing (STEP 3)." (PMID 41214301, 2026). "The RAIR signature stratified TCGA tumours with graded activation of these programs and was largely independent of BRAF and TERT promoter status, while preserving pathway associations when transferred to DepMap." (PMID 42232186, 2026). "STAT3 acts as a "double-edged sword": hyperactive STAT3 drives metastasis and BRAF inhibitor resistance in advanced carcinomas, yet paradoxically acts as a tumor suppressor by restraining the Warburg effect via non-canonical mitochondrial localization." (PMID 42193894, 2026). "High-fucosylation tumours exhibited elevated epithelial differentiation, MSI-H/BRAF-mutant enrichment, oxidative phosphorylation dominance, the complete absence of EMT and invasion programmes, and favourable prognosis (HR = 0.633, 95% CI: 0.470-0.853, p = 0.003)." (PMID 42117828, 2026). "Many type II RAF inhibitors, including tovorafenib, potently inhibit wild-type and altered BRAF and CRAF but are ARAF sparing, which may explain the pattern of pERK modulation observed in the NF1-LOF tumor cell lines treated with these agents." (PMID 40111124, 2025). "EGFR-inhibitors in any line were used in approximately 80% of patients eligible to intensive therapy, irrespective of sidedness in RAS&BRAF wild-type tumours in line with the Swedish guidelines." (PMID 40437037, 2025). "Furthermore, activation of MEK promotes tumor cell growth, proliferation, and survival, and, as such, dual inhibition of BRAF and MEK has been proposed as a therapeutic strategy in BRAF V600E-altered tumors." (PMID 40243903, 2025).
tumor (continued). "All currently approved combinations are hallmarked by the development of drug resistance, with 5‐year progression‐free survival estimated at less than 20%, leaving many patients with dual BRAF inhibitor (BRAFi) and MEK inhibitor (MEKi) resistant tumours and limited therapeutic options." (PMID 40135438, 2025). "While immune checkpoint inhibitors have shown significant efficacy in microsatellite instability-high (MSI-H) tumours and combined EGFR/BRAF inhibitor therapy has proven effective in BRAF V600E-mutant CRC, these treatments are only applicable to specific patient subgroups." (PMID 40539065, 2025). "Proximal tumours from carriers of the rs76011559 minor allele had similar frequencies of KRAS and BRAF mutations as compared to non-carriers, suggesting that the prognostic effect was independent of somatic mutation status." (PMID 39827162, 2025). "Finally, combined BRAF V600E and NTRK group gene hybridization are frequent in supratentorial neoplasms." (PMID 40361492, 2025). "In an NF–1 genetically engineered mouse model of plexiform neurofibroma lacking BRAF alterations, tovorafenib showed no antitumor activity; moreover, although not statistically significant, tumor volume increased in 2 out of 12 mice (approximately 17%)." (PMID 40867225, 2025). "In these instances, BRAF mutations detected in FFPE were also absent in LB, suggesting a low circulating tumor DNA." (PMID 40244273, 2025). "These include a high tumor mutational burden (46 mutations per Mb), the presence of NRAS and NF1 mutations, and the absence of BRAF V600E mutations." (PMID 40125165, 2025). "Tumor tissue exhibited loss of MLH1/PMS2 protein expression and microsatellite instability-high (MSI-H), with no detectable BRAF mutations or MLH1 promoter methylation." (PMID 41278281, 2025). "While clinical trials are in early phases, MEK inhibition with or without BRAF combination therapy has been shown to reduce tumor volume and influence survival in a limited number of patients." (PMID 40725122, 2025). "Although BRAF V600E retained statistical significance in multivariate analysis (HR = 2.45, p = 0.048), its lower hazard ratio relative to MTV and TLG suggests metabolic indices more directly quantify tumor aggressiveness." (PMID 40969790, 2025). "In pLGG, authors found that tumors with high tumor inflammation signature indicating a high immune cell infiltration such as BRAF mutant tumors, but not BRAF fusion tumors show the worst clinical outcome." (PMID 40588233, 2025). "Patient EP13 exemplifies this complexity as the BRAF p.Val600Glu was tested negative in the whole‐tumour sample but positive in mucinous, complex tubular and invasion front regions." (PMID 40302146, 2025). "Second, experimentally, this study validated Antrocin’s ability to simultaneously inhibit BRAF, MEK, and PI3K genes present in HCT116 and RKO cell lines, hence its broader anti-tumor effects in CRC, and compared its putative efficacy with that of FDA-approved standard inhibitors." (PMID 41009348, 2025). "Clinically, the presence of KRAS or BRAF mutations on ICI response has not been fully established and varies across tumour types." (PMID 40362630, 2025). "In other words, even after the traditional selection based on RAS and BRAF and tumor sidedness, approximately one-third of patients do not respond to EGFR-inhibition, indicating that additional molecular escape mechanisms limit therapeutic efficacy." (PMID 40940901, 2025). "If a tumor shows abnormal IHC/MSI and is negative for MLH1-PM and BRAF mutation, the patient is eligible for genetic testing for LS." (PMID 40988755, 2025).
tumor (continued). "CD24+CD271+ staining is therefore not specific to tumours that are BRAF/NRAS wildtype, nor to BRAF/NRAS mutant tumours." (PMID 40754577, 2025). "Targeted combination therapy with BRAF and MEK inhibitors is currently utilised in mutant BRAF tumours with or without immunotherapies." (PMID 40135438, 2025). "Finaly, the tumor mutational burden (TMB) was low, and no abnormalities were detected in BRAF, NRAS, HRAS, NTRK1/2/3, RET, or TERT." (PMID 40277780, 2025). "Tumour cells stained HMB‐45, Melan‐A, and SOX10 positive, AE1/AE3 negative, and carried an NRAS‐Q61 mutation with wild‐type BRAF, confirming cutaneous origin." (PMID 40918809, 2025). "For example, targeting mitogen-activated protein kinase (MAPK) pathway utilizing EGFR/MEK/BRAF inhibitors was shown to induce the expression of tumor neoantigens, promote the infiltration of CD8+ T cells to the tumor site and block the canonical oncologic signaling pathways." (PMID 40342408, 2025). "Patients without any tumor alterations in RAS/BRAF, or the simplified PRESSING panel were defined as ‘hyperselected’ (HS), whereas those with at least one such alteration were considered ‘gene altered’ (GA)." (PMID 41167084, 2025). "Third, biomarker analyses for RAS, BRAF, microsatellite instability, and circulating tumor DNA were not performed." (PMID 41199978, 2025). "BRAF/MEK inhibition promotes extracellular matrix (ECM) accumulation and remodeling during therapy‐tolerant residual disease, limiting CD8+ T cell access to tumor cells." (PMID 40847444, 2025). "PIK3CAmt status did not influence OS, neither in all patients, nor in analyses stratified by primary tumour location, RAS/BRAF-V600E mutation status, or treatment groups (data not shown)." (PMID 40437037, 2025). "Therefore, it is crucial to investigate how the tumor immune microenvironment is regulated in MSS BRAF mutant and BRAF wild-type CRCs to find better immunotherapies for these difficult-to-treat cancers." (PMID 41039118, 2025). "BRAF inhibitors (e.g., dabrafenib and vemurafenib) selectively occupy the ATP-binding pocket of BRAF-mutant monomers, thereby abrogating phosphorylation-dependent activation of the downstream MEK–ERK axis and suppressing tumor cell proliferation." (PMID 41480531, 2025). "Therefore, therapies targeting the MAPK/ERK pathway, such as BRAF and MEK inhibitors (e.g., vemurafenib, dabrafenib, trametinib, and selumetinib), can help control tumor growth and maintain dormancy." (PMID 39934876, 2025). "To identify independent factors associated with HMCC, we conducted a multivariate logistic regression analysis incorporating clinical variables (tumor location, size, lymphatic invasion, differentiation, MMR status, and BRAF status) and the relative abundances of selected bacterial taxa." (PMID 40522380, 2025). "This case highlights the importance of tumor molecular characterization, particularly in rare tumors, whereby identification of the BRAF:KIAA1594 gene fusion led to an appropriate selection of a type II BRAF inhibitor." (PMID 40377441, 2025). "To ensure that the apparent differences in CMS between BRAF mutation classes were not readily explained by potentially confounding variables, including MSI status and tumor location, we further performed multiple logistic regression analyses." (PMID 39751654, 2025). "First‐line targeted therapy in combination with chemotherapy is the standard of care for most metastatic CRC patients with the type of targeted agent (e.g., anti‐EGFR, anti‐VEGF) depending on tumor location and molecular status (microsatellite instability, RAS, and BRAF status)." (PMID 39865537, 2025).
tumor (continued). "Inhibition of BRAF may lead to reactivation of MAPK signalling, including EGFR and MEK, which are considered to be a dominant driver in many tumour types." (PMID 38773787, 2025). "Transcription data suggest the existence of a third tumor class with non-RAS and non-BRAF mutations, although more evidence is needed to confirm this." (PMID 41590496, 2025). "Conversely, patients with low TMB may gain more from adjuvant BRAF and MEK inhibitors, assuming that their tumour tissue is less heterogeneous." (PMID 39941847, 2025). "In BRAF-mutant CRC, restoring AIM2 expression significantly inhibited tumor growth and induced necrotic cell death in a caspase-1 dependent manner, further underscoring its role as a tumor suppressor." (PMID 40386782, 2025). "The tumor was microsatellite instability-high (MSI-H), with no BRAF mutation or MLH1 promoter methylation." (PMID 41278281, 2025). "No OS differences were seen between primary tumour locations in the BRAF-V600Emt and RASmt subgroups." (PMID 40437037, 2025). "Specifically, NTRK1 expression was significantly higher in right-sided tumours, late pathological T stage, non-metastasis (M0) stage, MSI positive state, the hypermutated/MSI subtype, BRAF mutation-positive, low FGA state, low aneuploidy state and high TMB." (PMID 41155675, 2025). "An EGFR inhibitor is added if the tumor is wild-type for KRAS, NRAS, and BRAF." (PMID 40004690, 2025). "In only 4 patients with multifocal disease, the largest tumor was BRAF negative while a smaller focus was BRAF positive; in 5 patients, the largest tumor was BRAF positive while a smaller focus was BRAF negative." (PMID 40237893, 2025). "In this patient population, BRAF p.V600E was only significantly associated with PTC subtype and follow-up time, but not with TN category, tumor size, nodal disease burden, tumor multifocality, extrathyroidal extension, treatment, recurrence, or mortality." (PMID 40237893, 2025). "Emphasizing maximal safe resection while minimizing treatment complications, along with the use of and BRAF-MEK inhibitors mentioned later, could enhance long-term tumor control and thereby improve social participation outcomes." (PMID 39841323, 2025). "MEK is a mitogen-activated protease downstream of BRAF, and MEK inhibitors reduce the activity of the MAPK signaling pathway by blocking the expression of MEK genes located downstream of BRAF genes and RAS genes, thereby inhibiting tumor cell proliferation." (PMID 39857808, 2025). "Interestingly, intra‐tumour endothelial cell count, although showing only a trend towards a worse prognosis in MISSONI, was prognostic in the BRAF cohort and highly significant when the two cohorts were combined." (PMID 39788558, 2025). "BRAF p.V600E positive and negative tumors were not significantly different based on tumor size, with BRAF p.V600E positivity in 77% of tumors ≤ 1 cm, 82% of tumors > 1 and ≤ 2 cm, 78% of tumors > 2 and ≤ 4 cm, and 72% of tumors > 4 cm." (PMID 40237893, 2025). "Recent studies have demonstrated that in patients with BRAFV600E-positive ATC, neoadjuvant therapy with dual BRAF/MEK inhibition using dabrafenib and trametinib can convert an initially unresectable tumor into a resectable state, thereby prolonging progression-free survival (PFS) and OS." (PMID 40927298, 2025). "Given the negative IHC staining of non-mutated tumours, IHC for BRAFV595E is confirmed to be specific for the mutant protein and does not cross-react with wild-type BRAF." (PMID 39591358, 2024). "In a KIAA1549::BRAF fusion-driven neural stem cells (NSC) model, CCL2 secreted by the tumor cells, and under the control of the MAPK pathway, was necessary for the recruitment of microglia cells promoting tumor formation." (PMID 38789691, 2024).